TLR9 (toll like receptor 9)
Diseases named in the same sentence as TLR9 in open-access papers (continued):
Sharing a sentence is not in itself a finding about the gene and the disease.
malaria (continued). "However, a recent study reported only a weak association of TLR9 polymorphism with severe malaria in Malawi and The Gambia, which was not replicated in family based cohort analyses." (PMID 24312262, 2013). "In addition, TLR9 engagement in DCs is required for natural Treg activation by malaria parasites." (PMID 22873687, 2012). "Because animal studies have implied a causal role for IFN-γ in the pathogenesis of cerebral malaria and IFN-γ levels were found higher in children with cerebral malaria who died as compared with survivors, these authors concluded that these TLR9 SNPs could play a role in modulating malaria severity." (PMID 22691414, 2012). "An exception might be represented by TLR9 T127C for which a significant correlation with an increased risk of developing malaria without any role in determining severity was found." (PMID 22691414, 2012). "However, it is still a matter of debate whether hemozoin itself binds this receptor, whether malaria pigment carries plasmodial DNA to TLR9 or whether the TLR9 ligand is a histone-DNA complex." (PMID 22096530, 2011). "In malaria blood-stage infection, parasite DNA, RNA and GPI anchors interact with TLR9, TLR7 and TLR2, respectively." (PMID 41398915, 2025). "EBV genomes are rich in CpG, which can increase TLR9 expression, creating another EBV foothold with the help of malaria." (PMID 37639483, 2023). "The interaction between the TLR4 and adjuvant enhance the immune response, while TLR3, TLR4 and TLR9 agonists have been used to improve vaccines against HBV, influenza, malaria and anthrax." (PMID 35371033, 2022). "Further studies have reported that IFN-γ release during murine malaria occurs downstream of TLR7 and TLR9 signaling and is thus dependent on the sensing of Plasmodium-derived nucleic acids." (PMID 30972055, 2019). "As such, studies in various mouse models have demonstrated that TLR9, TLR7, TLR4, and TLR2 play important roles in malaria immunity and cerebral, placental and other severe malaria pathology." (PMID 30619355, 2018). "Human TLRs that are known to be stimulated by malaria parasite-derived molecules include TLR2 (by glycosylphosphatidylinositol), TLR4 (by hemozoin), and TLR9 (by hemozoin and parasite DNA)." (PMID 30384846, 2018). "It needs validation with a larger sample size to confirm the importance of TLR9 and TLR5 in Pv-malaria." (PMID 28850598, 2017). "Patients with severe and mild malaria also showed increased surface expression of TLR2 and TLR4 on CD14+ monocytes and cDCs and decreased intracellular expression of TLR9 on pDCs." (PMID 27716849, 2016). "In particular, TLR3, TLR4 and TLR9 agonists have been shown to improve a number of vaccines, for example against HBV, influenza, malaria and anthrax, as well as some types of cancer." (PMID 26344622, 2014). "TLR9 mediates parasite recognition and initiates IFN-γ production to prime host innate responses against malaria." (PMID 22873687, 2012). "Recent studies have shown that malaria GPI and hemozoin are ligands for TLR2 and TLR9, respectively." (PMID 19710907, 2009). "If stimulation of TLR-7 and -8 by OPV, and TLR-9 by malaria confers temporary non-specific protection against an array of infections, then direct stimulation of these receptors by their specific synthetic agonists should also do so." (PMID 39534998, 2024). "A new formulation of the BK-SE36 vaccine candidate with a Toll-like receptor 9 stimulating adjuvant, CpG-ODN (K3) showed promising safety and immunogenicity results in malaria-naïve Japanese adults and more recently in malaria-exposed adults and children in Burkina Faso." (PMID 38400149, 2024). "It demonstrated that IL21R was expressed in healthy individuals in malaria-endemic areas before the start of the malaria season and down-regulated a week after treatment of the first acute malaria episode (in convalescence), while TLR7, TLR9, PRDM1, and CD38 showed the opposite pattern." (PMID 36380692, 2022).
malaria (continued). "Therefore, TLR9 and cGAS/STING are the major sensors for recognizing malaria parasite DNA for IFN-I responses." (PMID 33344264, 2020). "In addition to the role of plasmodial DNA to trigger TLR9, a novel TLR-independent DNA sensing pathway appears to be important in malaria recognition." (PMID 29495555, 2018). "While the involvement of TLR9, TLR4, and TLR2 in malaria immunity/pathology is evident from studies in both mouse malaria models and in humans, thus far none of the studies in endemic areas have revealed the association of TLR7 with human malaria immunity/pathology." (PMID 30619355, 2018). "These malaria-induced autoreactive T-bet+ B cells are generated through the activation of three receptors that act synergistically: interferon-γ receptor (IFN-γR), the B-cell receptor (BCR) and TLR9 that senses Plasmodium DNA." (PMID 29101363, 2017). "This possibility was suggested by the observation that the TLR9 agonist CpG failed to enhance specific MBC responses to a candidate malaria vaccine in Malian adults but not U.S. adults." (PMID 25955968, 2015). "Given that MBC stimulation can be driven by TLR4 and TLR9, the presence of circulating S. haematobium moieties may potentiate MBC response to malaria antigens by a TLR pathway, primed to an acute malaria infection." (PMID 22693628, 2012). "Therefore, it can be inferred that the TTAG haplotype may exert an increased TLR9 transcriptional activity resulting in higher TLR9 expression and subsequently higher pro-inflammatory cytokine production, thus conferring protection against symptomatic malaria phenotype." (PMID 22594374, 2012). "Adults with severe and mild malaria had increased expression of TLR2 and TLR4 on CD14+ monocytes and myeloid DCs and decreased expression of TLR9 on plasmacytoid DCs compared to adults with no history of malaria exposure." (PMID 19691558, 2009). "During malaria infection the Toll-like receptor 9 (TLR9) is activated through induction with plasmodium DNA or another malaria motif not yet identified." (PMID 19284650, 2009). "Similar frequencies of TLR2, TLR4, TLR9, and MAL genetic polymorphisms in populations with different histories of malaria exposure suggest that these innate immune pathways have not been under strong selective pressure by malaria." (PMID 19317913, 2009). "As TLR9 is an important innate immune sensor, it is not surprising that polymorphisms within this gene have been shown to associate with infectious and inflammatory diseases including HIV-1, SLE and malaria." (PMID 30651082, 2019). "Human pDCs but not mDCs express TLR9 and produce IFN-α and TNF-α in response to malaria parasites and that the robust production of IL-12 requires cooperation of both pDCs and mDCs." (PMID 24204889, 2013). "To investigate this possibility, we stimulated WT and ROCK1-deficient B cells in vitro in the presence/absence of key cues released during malaria, the CpG PAMP recognized by TLR9, and heme, a critical DAMP released during the hemolysis that the infection triggers." (PMID 39903532, 2025). "Indeed, mice bearing non-functional TLR9 or MyD88, or treated with a TLR7/TLR9 antagonist display a less pronounced inflammatory response and attenuated pathology during experimental malaria." (PMID 24453977, 2014).
colitis (76 papers, 2007 to 2025). Inflammation of the colon. "Such preventive effects of type I IFNs released following TLR9 activation on DSS-induced colitis are associated with intestinal barrier restoration." (PMID 41155222, 2025). "The suppression of TLR9-induced exacerbation of DSS-induced colitis was associated with the downregulation of type I IFN and Th1 responses in the colon." (PMID 39403381, 2024). "TLR9 also showed a protective function in the DSS colitis model; TLR9-deficient mice showed decreased expression levels of the intestinal repair genes such as hairy enhancer of split 1 and the vascular endothelial growth factor." (PMID 37191444, 2023). "Nucleic acid from gut bacteria is an essential source of TLR9 ligands critical for gut homeostasis, as apical TLR9 signaling in intestinal epithelial cells limits pro-inflammatory signals, and Tlr9−/− mice are more susceptible to colitis." (PMID 35529463, 2022). "First, TLR9 is the recognition receptor for mtDNA, which is highly ex-pressed in the intestine, and TLR9 deficiency protects against colitis, indicating that mtDNA-TLR9 signaling is critical and targetable pathway for IBD treatment." (PMID 36499214, 2022). "In Clostridioides difficile infections associated with colitis and intestinal inflammation, the pathogen’s exotoxin, toxin A (TcdA), organizes bacterial DNA into an optimal inter-DNA spacing to activate TLR9." (PMID 35972973, 2022). "TLR9-deficient mice were highly susceptible to experimental colitis and had a lower NF-κB activation threshold when compared to wild-type and TLR2-deficient mice." (PMID 32661259, 2020). "Moreover, TLR2-, TLR5- and TLR9-deficient mice are also more susceptible to chemically induced colitis." (PMID 36982420, 2023). "In fact, Tlr9−/− mice are more susceptible to a dextran sulfate sodium colitis model." (PMID 35670957, 2022). "Similarly, administration of individual synthetic ligands for TLR3, TLR7 and TLR9 had protective effects against colitis in mice, which were also associated with the induction of type I IFNs." (PMID 29570694, 2018). "In conclusion, our study showed that 1,25(OH)D3 relieved TNBS-induced colitis in rats by down-regulating TLR-9, which might be associated with inflammation." (PMID 26718757, 2015). "Interestingly, TLR9-deficient mice developed more severe colitis compared to wild-type controls." (PMID 37626745, 2023). "Furthermore, mouse models deficient in TLR9 are more susceptible to the development of colitis, and genetic polymorphisms of TLR9 are associated with and increased risk of IBD in humans, enhancing the critical role of bacterial DNA sensing in the development of IBD." (PMID 37566032, 2023). "CpG activation of TLR9 during the induction phase of DSS-induced colitis exacerbates colonic inflammation." (PMID 41155222, 2025). "Exacerbation of experimental colitis by TLR9-mediated type I IFN responses is consistent with enhanced expression of type I IFN signature genes in the colonic mucosa of patients with IBD." (PMID 41155222, 2025). "The effect of EBV and TLR9 inhibition on the severity of colitis in an IBD mouse model was evaluated using the DAI." (PMID 40722611, 2025). "In preclinical models, reducing luminal viral DNA attenuated TLR9 signaling and mitigated colitis, whereas exogenous CpG restored the inflammatory response and the TLR9 antagonist oligodeoxynucleotide 2088 reversed it." (PMID 41403883, 2025). "DNA from the VSL#3 probiotic formulation induced IL-6 and IL-12p40 secretion in bone marrow-derived macrophages (BMDMs) by activating NF-κB and JNK pathways and protected mice against DSS-induced colitis through a TLR9-MyD88-dependent mechanism." (PMID 41301527, 2025). "Of interest, it has been recently indicated that NOD2 activation in hematopoietic cells protected mice from TLR9-induced exacerbation of DSS-induced colitis by downregulating IFNα responses." (PMID 39346917, 2024).
colitis (continued). "CpG-mediated activation of TLR9 during the initial phase of DSS-drinking exacerbates DSS-induced colitis." (PMID 39403381, 2024). "provided evidence that TLR9 activation during the induction phase of DSS drinking exacerbates DSS-induced colitis through the induction of proinflammatory cytokine responses." (PMID 39403381, 2024). "TLR9 activation prior to the initiation of DSS drinking prevents the development of DSS-induced colitis in a type I IFN-dependent manner." (PMID 39403381, 2024). "We then turned our attention to the role of the crosstalk between NOD2 and TLR9 in experimental colitis." (PMID 39403381, 2024). "This exacerbation of DSS-induced colitis by the CpG-mediated activation of TLR9 was dependent on type I IFN signaling pathways, as mice deficient in the type I IFN receptor did not display aggravation of DSS colitis." (PMID 39403381, 2024). "Previous studies have reported that changes in the abundance of Bacteroides and Streptococcus affect the development of TLR9-mediated colitis and influenza." (PMID 37416999, 2023). "Previous studies demonstrated that bacterial DNA or its synthetic oligodeoxynucleotides (ODNs) analogues (immunostimulatory sequence (ISS) ODNs or CpG-ODNs), recognized mainly by TLR9, ameliorated the severity of colitis in murine models." (PMID 37566032, 2023). "In contrast, TLR9 deficient mice are more susceptible to DSS-induced colitis and administration of TLR9 agonist alleviates colitis, suggesting a protective role against intestinal barrier damage." (PMID 37215126, 2023). "We then measured fecal Lipocalin 2 (Lcn-2), a marker of colitis, and found that TLR9−/− mice presented higher levels of fecal Lcn-2 than WT mice." (PMID 35624094, 2022). "Dextran sulfate sodium (DSS)-colitis, an experimental mouse model of inflammatory bowel disease (IBD), is particularly useful for studying the contributions of the innate immune system (including TLR9-signaling) to the pathomechanism and therapy of colitis." (PMID 36359370, 2022). "It has been reported that phages can activate IFN-γ produced by CD4+ T cells via the nucleotide-sensing receptor TLR9, which accelerates intestinal inflammation and colitis, leading to a systemic inflammation response." (PMID 34442780, 2021). "In the experimental colitis model, the administration of the TLR-9 agonist improved clinical and histological parameters via the induction of IDO1, and the inhibition of IDO1 activity abrogated the protective effects." (PMID 33413597, 2021). "Overall, these findings provide evidence that L. johnsonii and B. thetaiotaomicron decrease the development of colitis mediated by TLR9 and promote the elimination of C. glabrata from the gut via chitinase-like and mannosidase-like activities." (PMID 32661259, 2020). "This in turn enables chitin digestion and the generation of small sized chitin particles that drive IL-10 production via TLR-9 sensing, promoting the attenuation of colitis and C. glabrata elimination." (PMID 32661259, 2020). "On the other hand, a different study showed that the administration of oligodeoxynucleotides with CpG motifs (bacterial cfDNA) that activate TLR9 significantly exacerbates the course of DSS-induced colitis." (PMID 31357438, 2019). "In preclinical studies in murine models of colitis, administration of the TLR9 oligonucleotide agonist suppressed the severity of colitis in RAG-/- mice." (PMID 31068803, 2019). "TLR9 was also shown to mediate the beneficial effects of probiotics on colitis development by sensing by the probiotics’ DNA and these effects were type I IFN dependent." (PMID 29570694, 2018). "Similar to c41, the antimalarial drug chloroquine has diverse effects on TLR signaling but particularly via TLR9 to alleviate murine colitis." (PMID 29515999, 2018).
colitis (continued). "Deletion of TLR4, TLR2, TLR5 and TLR9 as well as simultaneous deletion of TLR3 and TLR7 led to disturbed epithelial homeostasis and enhanced susceptibility to acute DSS-induced colitis, however with less severe pathology than in MyD88-deficient mice." (PMID 29570694, 2018). "TLR9 activation has been shown to prevent the development of mucosal inflammation and promote wound healing in several colitis models." (PMID 29441063, 2018). "A previous study showed that type I IFN, activated by the TLR9 signaling pathway, protects mice from experimental colitis." (PMID 29049372, 2017). "Consistent with the results of previous studies in IBD patient specimens and other animal experiments, our data showed that TLR9 was not only expressed in inflammatory cells in rats with colitis but also in epithelial cells and goblet cells." (PMID 26718757, 2015). "Systemic administration of TLR-9 ligands reduces the severity of colonic injury and inflammation in models of experimental colitis, in part through the TLR9-induced production of type I IFNs." (PMID 24454965, 2014). "In this study, our results have shown that Medilac-S alleviated the protein and mRNA expressions of TLR2, TLR4, and TLR9 in the colon mucosa in experimental colitis." (PMID 25276470, 2014). "Since activation of TLR9 transduces its signal by recruiting the adaptor molecule MyD88 we have then investigated the role exerted by FXR on development of TNBS colitis in TLR9−/− and MyD88−/− mice." (PMID 23372731, 2013). "Commensal and probiotic flora signal in part through TLR9-dependent induction of type I interferons such as IFNαA, which regulates inflammation through induction of IL-10 in adult models of colitis." (PMID 23272193, 2012). "We show that mild DSS-induced experimental colitis in mice permits evaluation of various effectors, including TLR9, in protection from intestinal damage, and for induction of intestinal restitution." (PMID 22853702, 2012). "Given the protective benefits of TLR9-induced Type I IFN in experimental colitis and reported success of recombinant IFN-β therapy in human colitis, we have developed a transgenic Lactobacillus strain that constitutively expresses murine IFN-β." (PMID 21365015, 2011). "TLR9 signalling is also required to mediate an anti-inflammatory effect induced by probiotics, in a mouse colitis model." (PMID 21813005, 2011). "Blockade of either TLR9 signaling or IFNAR1 inhibits the protective capability of TLR9 agonists, such as probiotics, in murine colitis." (PMID 21365015, 2011). "Administration of LPS or CpG-ODN (a TLR9 agonist) to rabbits or mice was shown to enhance experimentally-induced colitis or ileitis." (PMID 20161736, 2010). "There, however, seems to be no sufficient explanation for the strong protective qualities of TLR9 activation in colitis models as not only orally administered CpG-ODN but also systemic CpG-ODN application protects from intestinal inflammation." (PMID 21188217, 2010). "CpG oligonucleotides have also been shown to prevent murine colitis, supporting also the essential role of TLR9 signaling." (PMID 17375199, 2007). "Our study indicates that EBV aggravates colitis symptoms in an IBD mouse model through TLR9." (PMID 40722611, 2025). "Activation of TLR9 initiates a signaling cascade that promotes an anti-inflammatory profile, effectively contributing to the reduction of inflammation across multiple experimental colitis models." (PMID 40423637, 2025). "Thus, MDP-mediated activation of NOD2 prevents the exacerbation of DSS-induced colitis induced by TLR9 activation." (PMID 39403381, 2024). "The severity of colitis was significantly reduced following treatment with TLR9 agonist." (PMID 37626745, 2023). "TLR9’s role in the pathogenesis of colitis has been studied in murine experimental models." (PMID 37626745, 2023).